POMC (proopiomelanocortin)
Diseases named in the same sentence as POMC in open-access papers (continued):
Sharing a sentence is not in itself a finding about the gene and the disease.
Obesity (continued). "Our results reveal a necessary mechanism through which obesity medications d-fenfluramine and sibutramine achieve their therapeutic appetitive effect, via activation of ARC POMC neurons." (PMID 25051442, 2014). "Here we distill a critical and necessary mechanism responsible for communicating the anorectic effect of obesity medications d-fenfluramine and sibutramine to ARC POMC neurons." (PMID 25051442, 2014). "Increased SOCS-3 expression in POMC neurons inhibits activation of signal transducer and activator of transcription (STAT)-3 and results in hyperphasia and obesity." (PMID 23696840, 2013). "A similar degree of obesity and adiposity is seen in mice with inactivation of STAT3 in POMC neurons." (PMID 23341784, 2013). "In general, animal models of obesity present increased expressions of the orexigenic, anti-thermogenic NPY and MCH and reduced expressions of the anorexigenic, pro-thermogenic POMC and CART." (PMID 22279596, 2012). "Recently, these knockout models have allowed the identification of several singular molecular components for the development of obesity, e.g. of leptin, insulin-(receptor), interleukin-6, GIP-(receptor), pro-opiomelanocortin (POMC) and derivatives." (PMID 20862277, 2010). "Previously, we showed that established maternal obesity and litter size reduction reciprocally altered hypothalamic NPY and POMC mRNA expression." (PMID 19606226, 2009). "This study, employing multiple animal models, demonstrated that while chronic inhibition of POMC neurons or paraventricular MC4R-expressing neurons induced significant obesity, chronic activation of these neuronal populations failed to reduce body weight." (PMID 40130157, 2025). "Notably, rare, pathogenic mutations in all the genes involved in leptin driven melanocortin pathway (LEP, LEPR, POMC, PCSK1, MC4R, primarily) lead to severe early-onset obesity accompanied by eating disorders." (PMID 39237720, 2025). "Similarly, maternal diabetes and obesity also induce hypothalamic changes that result in an imbalance in AgRP/NPY and POMC expression during adulthood." (PMID 40474775, 2025). "Selective ablation of these neurons enhances POMC neuron activation under high-fat diet conditions, reduces feeding, and protects against obesity without affecting normal chow consumption." (PMID 40130157, 2025). "One concern is that Set is used for weight loss only in patients with mutations in the POMC/leptin/MC4R pathways, but not in the most common polygenic form of obesity." (PMID 40232848, 2025). "Mice lacking SOCS3 in the brain or specifically in POMC neurons exhibit enhanced leptin sensitivity and are resistant to diet-induced obesity." (PMID 41516046, 2025). "NaChBac-mediated activation of POMC neurons did not reduce body weight, whereas Kir2.1-mediated chronic inhibition of POMC neurons led to obesity." (PMID 39584979, 2024). "Under normal conditions, hypothalamic reactive oxygen species (ROS) function to maintain energy homeostasis through balancing the activation between POMC and NPY/AgRP neurons, but excessive ROS would damage these hypothalamic neurons, resulting in disturbed energy homeostasis and obesity." (PMID 38397850, 2024). "Additionally, using an HFD-induced mouse obesity model to investigate the effects of SGLT2 inhibitors, we found changes in the expression of AgRP and POMC mRNA depending on the duration of SGLT2 inhibitor treatment." (PMID 39057086, 2024). "Another study showed that hypermethylation of the POMC promoter gene and hypomethylation of the NPY promoter gene interferes with the binding of transcription factors, and blocks the effect of high leptin levels, thus leading to obesity." (PMID 38707092, 2024).
Obesity (continued). "Under this condition, POMC-MC4Rflox/flox mice exhibited a remarkably increased body weight from the age of 13-weeks old compared with control mice, accompanied by an increased food intake, indicating that MC4R is involved in developing of obesity." (PMID 38448811, 2024). "On the other hand, loss of LepR in POMC/CART, but not AgRP/NPY, neurons in the adult mice promotes obesity only when fed HFD These results suggest that the primary target of leptin is context-dependent." (PMID 37547309, 2023). "More specifically, mice lacking AMPK in POMC neurons developed obesity due to increased food intake and decreased energy expenditure." (PMID 38027481, 2023). "The melanocortin system plays an important role on the regulation of appetite, energy expenditure, and metabolism, therefore, impairments in the POMC and melanocortin 4 receptor (MC4R) pre- and post-translational processing are forerunners for the development of obesity." (PMID 36969815, 2023). "Further, these alterations in gut microbiota have been shown to promote important changes in satiation signals including gut hormones (leptin, ghrelin, GLP-1, peptide YY and CCK) and orexigenic and anorexigenic neuropeptides (AgRP, NPY, POMC, CART) that influence hyperphagia and therefore obesity." (PMID 37571301, 2023). "We appreciate that heterozygous mutations in genes such as ALMS1, BBSs, LEPR, POMC, and PCSK1 have not been shown to be sufficient to cause the disease of obesity, except for the complete loss-of-function mutations of PCSK1, but not for POMC or LEPR mutations." (PMID 37835041, 2023). "Mice lacking SOCS3 in the brain or POMC neurons display improved leptin sensitivity and resistance to diet-induced obesity." (PMID 38027481, 2023). "Several individuals suffer from a deficiency in POMC or α-MSH, leading to a lack of MC4R functioning and obesity." (PMID 37937009, 2023). "In our studies, we did not observe any impact of the known deletion in the POMC gene on body weight or obesity." (PMID 37799139, 2023). "To further examine whether chronic activation of POMC neurons could reverse any aspect of obesity, we first fed a cohort of POMC-Cre mice with high-fat diet (HFD) for 10 weeks, which induced obesity." (PMID 37069175, 2023). "Other mutations within the leptin–melanocortin pathway, such as in proopiomelanocortin (POMC), melanocortin receptor 4 (MC4R), brain-derived neurotrophic factor (BDNF), and the tyrosine kinase receptor B (NTRK2) genes, can also contribute to obesity." (PMID 37762850, 2023). "Similar to diet-induced obese mice, we observed no significant impact on obesity in ob/ob mice with α-MSH overexpression in Arc POMC neurons, compared to controls." (PMID 37069175, 2023). "Although TLR4 plays an important role in obesity and metabolic dysfunction, it remains unclear about the specific role of TLR4 in POMC neurons." (PMID 37028769, 2023). "Deletion of LepR gene specifically in AgRP/NPY, but not in POMC/CART, neurons in the adult mice (to avoid compensatory effects of gene deletion) causes obesity under a standard chow diet." (PMID 37547309, 2023). "In anorexigenic proopiomelanocortin (POMC) neurons, AIF inhibition results in partial damage to mitochondrial OXPHOS and enhances the availability of fatty acids and ROS formation, which ameliorate systemic glucose metabolism in obesity." (PMID 35090552, 2022). "It was recently demonstrated in mice specifically lacking Tbx3 from POMC neurons that Pomc expression was diminished leading to hyperphagia and obesity." (PMID 35044906, 2022). "Based on the minocycline data, we hypothesized that the more specific microglial inhibitor CX3CL1 would restore POMC neuron function during HFD feeding, which might account for its anti-obesity properties." (PMID 35742824, 2022).
Obesity (continued). "The increased level of ROS and NO in the first-order neurons into arcuate nucleus, and the aberrant functioning of orexigenic Agouti-related protein (AgRP)/Neuropeptide Y (NPY), anorexigenic pro-opiomelanocortin (POMC)/cocaine- and amphetamine-regulated transcript (CART) can lead to obesity." (PMID 36501129, 2022). "Hypothalamic pro-opiomelanocortin (POMC) neurons have been shown to regulate food intake and body weight and in female mice, ERα expressed in POMC neurons and steroidogenic factor-1 (SF-1) neurons mediated the anti-obesity effects of E2 administration." (PMID 35873031, 2022). "We screened a targeted 20 patients with a phenotype indicative of defects in the POMC pathway (extreme obesity and red hair color) for ASIP variants originally suspected but not diagnosed for POMC deficiency." (PMID 36536132, 2022). "Since PC1/3 cleaves POMC to the anorectic α-MSH, the canonical view is that PC1/3-related obesity could be regulated by reduced processing of POMC." (PMID 35963866, 2022). "Evidence on the subject has found that in POMC neurons, overexpression of the unfolded protein response transcription factor (Xbp1s) decreases the expression of PTP1B and SOCS3, improves leptin and insulin sensitivity, and protects against obesity." (PMID 35563589, 2022). "Genes encoding leptin (LEP), leptin receptor (LEPR), melanocortin 4 receptor (MC4R), proprotein convertase subtilisin/kexin type 1 (PCSK1), proopiomelanocortin (POMC), kinase suppressor of ras 2 (KSR2), adenylate cyclase 3 (ADCY3), and others contribute to the development and progression of obesity." (PMID 36141228, 2022). "These evidences suggested that potential drug candidates which could regulate the hypothalamic H1R-AMPK signaling, POMC expression and BAT thermogenesis might significantly prevent olanzapine-induced obesity." (PMID 35365730, 2022). "POMC deficiency results in the absence of its cleavage products, and inactivation of MC4R, thus causing hyperphagia, severe obesity, and red hair." (PMID 36452324, 2022). "An agonist of the MC4R, used in individuals with severe obesity due to either POMC, PCSK1, or LEPR deficiency, and should not be used for other types of obesity such as general obesity." (PMID 34552557, 2021). "In fact, patients with monogenic POMC and PC1 defects show altered pigmentation and auburn hair, due to the lack of α-melanocyte-stimulating hormone, and hyperphagic obesity usually presenting during infancy, due to defective POMC hypothalamic signaling." (PMID 34489864, 2021). "Mice lacking SIRT1 in proopiomelanocortin (POMC) neurons on a high-fat diet (HFD) are vulnerable to diet-induced obesity because of reduced energy expenditure even when regular chow diet (RCD)-fed conditions do not alter body weight or adiposity in these mice." (PMID 34046646, 2021). "Rather unexpected, affected animals showed no overt phenotype, specifically, no signs and symptoms of obesity, despite the fact that POMC mutations affecting production and/or function of β-MSH are associated with obesity in human." (PMID 32369484, 2020). "We also found a possible mechanism of CAP’s anti-obesity effect by enhancing PYY and GLP-1excretion in intestinal epithelial cells, which suppress NPY- and AgRP-expressing neurons and activate POMC- and CART-expressing neurons in the ARC of the hypothalamus, resulting in lower food intake." (PMID 32180694, 2020). "In contrast, these mutant mice on a high-fat diet (HFD) are vulnerable to diet-induced obesity due to reduced EE, because SIRT1 in POMC neurons is required for the brown adipose tissue-like remodeling of the perigonadal white adipose tissue through sympathetic activation." (PMID 32143417, 2020). "Many genes implicated in monogenic obesity have also been flagged in these large-scale obesity GWAS, including LEPR, MC4R, and POMC, although they are usually not the most prominent findings." (PMID 33233816, 2020).
Obesity (continued). "However, obesity appears to alter the ongoing activity and responsiveness of arcuate NPY and POMC neurons in a sexually dimorphic way, such that SNA increases in males but not females." (PMID 32160920, 2020). "Sh2b1ΔPOMC mice with POMC neuron-specific ablation of Sh2b1, unlike Sh2b1ΔLepR mice, did not develop obesity and insulin resistance." (PMID 32251290, 2020). "The ARH has not been primarily viewed as a dimorphic structure, but recent studies showed differences between males and females in the number of ARH POMC neurons, their firing rate, the development of diet-induced obesity, and the activation of STAT3 in POMC neurons." (PMID 33253166, 2020). "POMC neuronal damage during diet-induced obesity is further supported by Cakir and colleagues, whose findings showed that HFD exposure for 12 weeks in SD rats induces ER stress in the arcuate nucleus and disrupts post-translational processing of POMC." (PMID 33092099, 2020). "Diet‐induced DNA methylation changes occurring within ARC genes, particularly POMC and INS‐R, which prevents an appropriate response to leptin and insulin, thereby affecting energy homeostasis, subsequently leading to the development of obesity and MeS." (PMID 31660128, 2019). "Consistently, previous work demonstrates that the inhibition of autophagy in proopiomelanocortin (POMC) neurons leads to metabolic disorders, including obesity and insulin resistance; however the mechanism by which this occurs is still largely unknown." (PMID 30972025, 2019). "With diet-induced obesity/insulin resistance brought on by long-term exposure to a HFD in males, the ability of these neurons to execute their functions becomes impaired, perhaps through augmented EC signaling at VMN SF-1/ARC POMC synapses." (PMID 29973869, 2018). "In an experiment, knocking out Dicer in proopiomelanocortin (POMC) precursor-expressing cells in arcuate nucleus of the hypothalamus (ARC) has led to increased food intake, hyperglycemia, impaired glucose tolerance, and secondary obesity." (PMID 30648107, 2018). "The proportion of POMC neurons activated by insulin was dependent on the regulation of insulin receptor signaling by the phosphatase TCPTP, which is increased by fasting, degraded after feeding and elevated in diet-induced obesity." (PMID 30230471, 2018). "The delay in onset of obesity suggests that impaired Sel1L-Hrd1 ERAD function attenuates, rather than completely blocks, POMC maturation within the ER, and thus, more time is required to develop the obesity phenotype." (PMID 29457782, 2018). "Activation of small population of POMC neurons in the nucleus of the solitary tract of the hindbrain rapidly inhibits feeding, however their ablation does not produce obesity." (PMID 28360832, 2017). "On the other hand, POMC-specific PTEN−/− mice develop leptin resistance and obesity, suggesting that chronic elevation of PIP3 in POMC neurons may interfere with hypothalamic leptin activity." (PMID 28270795, 2017). "Likewise, mice overexpressing a constitutively active version of STAT3 in POMC neurons show elevated SOCS3 expression and develop obesity as a result of hyperphagia and decreased POMC expression accompanied by central leptin resistance." (PMID 28270795, 2017). "PNE does not result in obesity and type 2 diabetes but instead enhances leptin-melanocortinergic feeding and body weight regulation via POMC neurons in adult offspring." (PMID 27609221, 2016). "In the hypothalamus, neurons expressing pro-opiomelanocortin (POMC), defined as part of the melanocortin system, play an important role in regulating food intake and energy expenditure, which is considered a promising target for the treatment of obesity." (PMID 27558934, 2016). "In our current study, we demonstrated that mice lacking IRE1α specifically in POMC neurons are resistant to obesity and obesity-related metabolic disorders, the effects of which were mediated by increased energy expenditure." (PMID 27558934, 2016).
Obesity (continued). "In rats with diet-induce obesity, brain SIRT1 inhibition increased POMC that leads to an increase in α-melanocyte-stimulating hormone (α-MSH), which could in turn increase thyroid releasing hormone and T3 levels." (PMID 25805970, 2015). "So far, several genes, such as proopiomelanocortin (POMC), leptin receptor (LEPR), leptin (LEP), proconvertase 1 (PC1), and melanocortin 4 receptor (MC4R), have been confirmed as the casual genes to the onset of monogenic obesity." (PMID 24707501, 2014). "Heterozygous null mutations in POMC and loss-of-function mutations in α- and β-melanocyte-stimulating hormone (α- and β-MSH) significantly increase obesity risk but are not invariably associated with obesity." (PMID 25154910, 2014). "Like POMC, NPY signaling may be influenced by ER stress induced by obesogenic diet, and may play a role in the development of obesity." (PMID 26237477, 2014). "In conclusion, we show that POMC neurons of DIO mice are resistant to STAT3 activation by leptin and that over-expression of LepRb only in POMC neurons is sufficient to potentiate the development of diet-induced obesity." (PMID 22276206, 2012). "We here demonstrate that specifically arcuate POMC neurons of DIO mice are resistant to LepRb-STAT3 signaling, suggesting an important role of those particular neurons in the development and/or maintenance of diet-induced-obesity." (PMID 22276206, 2012). "None of the genotyped variants in genes for monogenic obesity reached genome-wide significance in our GWAS, although several variants in CRHR1, CRHR2, MCHR1, MC3R, MC4R and POMC were nominally associated." (PMID 23251661, 2012). "The result that over-expression of LepRb in POMC neurons increases body weight in HFD mice is initially surprising, considering the well known anti-obesity effect of the leptin-LepRb system and our recent report showing that expression of LepRb in POMC neurons of Leprdb/db mice reduces body weight." (PMID 22276206, 2012). "However in mice, chronic activation of the mTOR/S6K pathway by POMC neuron-specific deletion of TSC1, demonstrate leptin resistance, hyperphagia and obesity, presumably due to an alteration of the hypothalamic neurocircuitry of energy balance." (PMID 22291999, 2012). "In our study we showed that hypothalamic progenitor cells express feeding-related neuropeptides and differentiate to mature neurons including those described to be affected by hypothalamic neurodegeneration in obesity and Huntington disease: NPY, AGRP, POMC, CART and Orexin-A neurons." (PMID 21589937, 2011). "Although the patient did not have red hair, gene sequencing of POMC was performed due to her obesity and adrenal insufficiency." (PMID 21860632, 2011). "For example, PIP3 production was elevated in POMC neurons in which the phosphatase and tensin homolog (Pten), a PIP3 phosphatase, was specifically deleted, and these mice were hyperphagic and displayed diet-sensitive obesity." (PMID 19883613, 2009). "The human POMC cluster C4-374, corresponding to the mouse Glp1r-expressing POMC neurons, instead expresses the calcitonin receptor (CALCR), highlighting the interspecies heterogeneity of POMC populations, which has direct implications for currently licensed obesity therapies." (PMID 39910307, 2025). "We next built a prioritization score that weighs each of the eight methods based on whether or not they prioritized one or more of the six established obesity genes located in any of the 536 BMI-associated loci (i.e., LEPR, POMC, PCSK1, DGKI, SH2B1, and MC4R)." (PMID 38754426, 2024). "Thus, the lack of body weight reduction in both chow and HFD-fed conditions suggests that activation of POMC neuron activity fails to reduce body weight or reverse obesity." (PMID 37069175, 2023). "POMC and NPY could, therefore, be used as pharmaceutical targets for reversing obesity." (PMID 37899888, 2023).